ENSG00000252238
Gene: Small nucleolar RNA gene on chromosome 2 (4,827,001 to 4,827,084, reverse strand). Ensembl gene ENSG00000252238.
Gene Ontology:
Biological process: RNA processing
Cellular component: nucleolus
Homologues: Orthologues: mouse Gm55776 (62% identical). Paralogues in human: SNORA31 (86% identical), SNORA31B (68% identical).